VIM (vimentin)
Diseases named in the same sentence as VIM in open-access papers (continued):
Sharing a sentence is not in itself a finding about the gene and the disease.
cancer (continued). "The results suggested that DADS downregulated LIMK1 expression to decrease the expression of vimentin, CD34, and Ki-67; increase E-cadherin expression; and impede cancer cell proliferation, angiogenesis, and EMT alteration, thereby inhibiting invasion and metastasis." (PMID 28358024, 2017). "EMT plays an essential role in cancer cell invasion and metastasis, and many different biomarkers have been identified to involve in EMT, such as E-cadherin, N-cadherin, fibronectin, and vimentin." (PMID 29340100, 2017). "It included a number of genes with obvious cancer relevance including CD44, catenin b1 (CTNNB1), vimentin (VIM), cathepsins B and S (CTSB, CTSS), MMP9, XIAP, JunD, numerous proto-oncogenes (REL, YES, SET, FGR, CRK), and HSP90AA1 (which is a chaperone which stabilizes MIF as a client)." (PMID 28957348, 2017). "Vimentin is an intermediate filament protein that is ubiquitously expressed in normal mesenchymal cells to maintain the cellular architecture and tissue integrity, and it also participates in tumorigenesis, EMT, and the metastatic spread of cancer." (PMID 28570699, 2017). "Vimentin expression is a marker of EMT and cancer metastasis." (PMID 28968963, 2017). "The positive rate of Vimentin, VE-cadherin, and Galectin-3 expression in the presence of Runx2 was higher than in cancer cells that did not express Runx2, while the positive rate of E-cadherin in Runx2-positive cells was lower than in the Runx2-negative group." (PMID 28264434, 2017). "Furthermore, the overexpression of the EMT marker vimentin and MMP7 suggests that cancer cell invasion in our tumouroids is an active process dependent on the proteolysis of the surrounding ECM." (PMID 28276469, 2017). "For further analyses, since ZEB1 is one of the major transcription factors that promote EMT in various cancer cells, we depleted ZEB1 in ES-2 and SKOV3 cells and examined the expression of E-cadherin as an epithelial marker, and vimentin and N-cadherin as mesenchymal markers." (PMID 29245917, 2017). "We also observed that A2780 cells treated with exosomes from platinum-resistant cells displayed a 2- to 5-fold (P<0.05) decrease in KLF4, a transcription factor that regulates genes essential to EMT including E-cadherin and vimentin and has been shown to regulate EMT in multiple types of cancers." (PMID 28060758, 2017). "In our study, MET-related markers including CD324, Slug, Twist and vimentin did not change after cancer cell treatment." (PMID 28102844, 2017). "The results suggested that DADS could downregulate the expression of LIMK1 to impair the expression of vimentin, CD34, and Ki-67 and increase the expression of E-cadherin, thereby inhibiting cancer growth, invasion, and metastasis." (PMID 28358024, 2017). "We observed that cancer sera-treated cells had completely changed their fate since all developing tumors stained negative for vimentin, which is normally expressed on fibroblasts." (PMID 28854931, 2017). "This CRC7.4 line expressed cytokeratin, but not vimentin, suggesting the epithelial origin of the cancer cells." (PMID 29173894, 2017). "First, vimentin is a canonical biomarker of EMT and metastasis in numerous cancer types." (PMID 27602764, 2016). "Other CAF biomarkers in use include vimentin (VIM), fibroblast activation protein (FAP), and fibroblast-specific protein 1 (FSP-1).In addition, cytokeratin (CK) is negative in CAFs which differentiates them from epithelium-originated cancer cells." (PMID 26954362, 2016). "As an important marker of the EMT, vimentin is essential to the progression and prognosis of cancer through the EMT and the corresponding signaling pathways, which contribute to the tumorigenesis, metastasis, invasion and drug resistance of various cancers." (PMID 27657690, 2016). "They and vimentin are, however, aberrantly expressed in cancer cells and are thus sometimes expressed in non-epithelial immortalized cell lines." (PMID 29056733, 2016).
cancer (continued). "Downregulation of vimentin also decreased expressions of proteins participating in anchoring junction and tight junction in A2780-VIM-KN cells, which destabilized both anchoring junction and tight junction, leading to the emergence of cancer stem cell." (PMID 27322682, 2016). "Ectopic STAT3 expression clearly increased the mRNA expression of mesenchymal markers including Vimentin and N-cadherin, and decreased the expression of epithelial marker E-cadherin in MCF7 and T47D cells, suggesting that STAT3 promotes EMT in cancer cells." (PMID 26716902, 2016). "EMT has been demonstrated to play an essential role in cancer cell invasion and metastasis, and many different biomarkers involved in EMT have been identified, including E-cadherin, N-cadherin, fibronectin, and vimentin." (PMID 27136519, 2016). "Vimentin was strongly detected in stromal cells, whereas it was absent in cancer cells showing the localization of FAM83H to nuclear speckles (arrows)." (PMID 27681590, 2016). "Our observation that vimentin was expressed in some benign prostate epithelial cells, but not within cancer cells, is intriguing as vimentin is reportedly overexpressed in invasive PCa cells undergoing EMT." (PMID 26701730, 2016). "High L1CAM expression was frequently observed at the invasive front of cancers with high vimentin and absent E-cadherin expression." (PMID 27833079, 2016). "The exact reason of the difference in expression pattern of vimentin protein among the different grades of the carcinomas is not fully understood." (PMID 27190522, 2016). "Similar experiments performed with PSN-1 cells showed that the morphology of the cancer cells exposed to CM from senescent HPMCs remained squamous, and that the level of E-cadherin and vimentin in these cells was unaltered (not shown)." (PMID 26284488, 2015). "In the present study, we investigated the expression of three EMT-related proteins, including E-cadherin, N-cadherin, and vimentin, in PGCCs with budding daughter cells and control cancer cells without CoCl2 treatment." (PMID 26702618, 2015). "In some cancers, a mechanism involving the AEG-1-Vimentin interaction has been reported." (PMID 25880337, 2015). "In fact, cancer cell lines range from small, highly proliferative cells expressing the epithelial marker E-cadherin but not the mesenchymal marker vimentin, to another extreme of large, mesenchymal cells expressing vimentin but not E-cadherin." (PMID 26702357, 2015). "As is the case with the SFDM sphere-induced tumors, these tumors were positive for CD44, vimentin, laminin and diffusely positive for CD31 and CD34 staining, suggesting that the anti-miR-17 cancer sphere cells were able to recapitulate both renal and endothelial cell types of RCC." (PMID 25011053, 2015). "Vimentin has become an important biomarker for epithelial-mesenchymal transition (EMT), a highly dynamic cellular process involved in the initiation of metastasis and cancer progression." (PMID 26292717, 2015). "The current study demonstrated that vimentin serves as a regulator to maintain intracellular mechanical homeostasis by mediating cytoskeleton architecture and the balance of cell force generation in EMT cancer cells." (PMID 25965826, 2015). "It is hypothesized that podoplanin is likely to be important in the process of EMT, as a number of cancer cells in ESCC co-expressed podoplanin and vimentin." (PMID 26095281, 2015). "We speculated that TQ treatment decreases the expression of TWIST1 and its downstream protein N-Cadherin in cancer cells, while SNAIL1 and Vimentin were partially affected in cell specific manner." (PMID 26023736, 2015). "In addition, the epithelial marker, E-cadherin, and the mesenchymal markers, N-cadherin and vimentin, are regarded as important markers of EMT, and are widely used in invasion and metastasis cancer research." (PMID 26702618, 2015).
cancer (continued). "Consistent with the real-time PCR analysis, the down-regulation of FoxM1 expression significantly enhanced E-cadherin expression and attenuated Vimentin and Snail expression in FoxM1-knockdown SW620 cancer cells compared with those of control cells at the mRNA levels." (PMID 25935853, 2015). "In cancer cells, EMT is a phenotypic change, by which epithelial cells lose their polarity and epithelial markers, such as E-cadherin, and acquire migratory factors that are characteristic of fibroblasts, such as snail and vimentin." (PMID 26095281, 2015). "The mechanisms that drive EphB4 over-expression in cancer cells have not been determined although EphB4 itself was recently reported to regulate the estrogen receptor α and vimentin in breast cancer." (PMID 25831049, 2015). "Vimentin expression was analyzed in the cancer cells present in each lymphatic vessel and compared with the expression of vimentin in the cancer cells in the adenocarcinomas without an MPP component." (PMID 25120667, 2014). "Surprisingly, vimentin levels were not altered upon fluvastatin in normal mammary epithelial cells indicating its active role in cancer cell proliferation." (PMID 25268751, 2014). "To investigate the role of vimentin in detail we used siRNA technology to knock down vimentin because we were able to detect vimentin by Western blot analysis in two described vimentin negative cancer cell lines like HT29 and A549 cells." (PMID 24967582, 2014). "Unlike the four markers which were detected in interstitial cells (such as α-SMA and vimentin) or the cancer cells membrane (such as CK-19), TGF-β and FAP expression was detected in the cytoplasm of cancer cells while twist was located in both cytoplasm and nucleus." (PMID 25189096, 2014). "The cancer-associated stromal cells were SMA-positive, vimentin-positive and cytokeratin-negative, confirming their identity as myofibroblasts." (PMID 25011545, 2014). "Immunohistochemical evaluations of cytoplasmic filaments indicated that HRs- FMCs are vimentin+, CK14+, and CK5_6+ carcinomas that may resemble the TNBCs (basal like/claudin low) described in women." (PMID 25249140, 2014). "A high proportion are also reactive for vimentin, which is not often detected in carcinomas, a helpful feature that aids in distinguishing between the two." (PMID 25068699, 2014). "Positive signals for nuclear vimentin were detected in 15.7% (14/89) of cases, with vimentin only expressed in carcinoma tissues that over-expressed AQP3 and lacked expression of E-cadherin." (PMID 24887009, 2014). "Vimentin is a well-known marker of epithelial-mesenchymal transition (EMT), a process which plays a crucial role in carcinogenesis by enabling cancer cell dissemination from metastatic tumors, promoting cell invasion as well as acquisition of therapeutic resistance." (PMID 23295955, 2013). "Vimentin and fibronectin are commonly used to identify cells undergoing EMT in cancers." (PMID 23937725, 2013). "Third, consistent with recent studies highlighting a role for EMT after ADT in facilitating human PCa progression and metastasis, cancer cells in CR-TSGs exhibited EMT by simultaneously expressing both mesenchymal and epithelial cell markers, VIM and K18, respectively." (PMID 23985008, 2013). "Specifically, a rare population of cancer cells expressing both VIM and K18 was observed in CR-TSGs but not in control TSGs." (PMID 23985008, 2013). "In clinical specimens of RCC, the expression levels of VIM were significantly upregulated in cancer tissues compared to adjacent non-cancerous tissues." (PMID 22766839, 2012). "In addition, control cancer cells expressed more epithelial-to-mesenchymal transition (EMT)-related molecules such as N-cadherin and vimentin, compared with either TG2-knocked-down (shTG2_MB231#1) or IL-6-knocked-down cells (shIL-6_MB231#6)." (PMID 21967801, 2011).
cancer (continued). "We observed that NRP2 expression is correlated with vimentin expression and with a lack of E-cadherin expression in these cancer cell lines." (PMID 21747928, 2011). "Sections of benign breast tissue specimens without any detectable cancer cells were utilised as positive controls for the expression of GSTPi and vimentin, and negative for α-SMA expression." (PMID 21897388, 2011). "In addition, we found major populations of cells that express vimentin with CD44 and only a minor subset that express these molecules with CD133, a potential marker on cancer stem cells." (PMID 24212937, 2011). "Interestingly, Vimentin, an intermediate filament cytoskeletal protein and a marker of EMT was shown by this study to be significantly up-regulated in CA1a high grade cancer cells." (PMID 20543960, 2010). "Women with vimentin-positive cancers were significantly younger when compared with vimentin-negative ones." (PMID 19695088, 2009). "Immunohistochemistry revealed that cancer cells were positive for cytokeratins and vimentin to a varying degree and negative for Desmin, S-100, Osteopontin, BMP-2 or BMP-4." (PMID 19040765, 2008). "Studies of other G-CSF-producing cancers have not investigated vimentin immunoreactivity, so further examination is required." (PMID 18588705, 2008). "No influence of vimentin coexpression on the overall survival prognosis of Ck 8/18 and Ck 19 positive carcinomas was observed." (PMID 16412231, 2006). "In summary, the proteomic characterization of vimentin-positive EVs not only broadens our knowledge of the molecular drivers of EMT and immune modulation but also provides a promising target for therapeutic interventions in both cancer and regenerative medicine." (PMID 40618999, 2025). "Thus, restoring E-cadherin expression and inhibiting the expression of N-cadherin/vimentin could potentially prevent the initiation of EMT, thereby reducing the migration and invasiveness of malignant tumors." (PMID 40806251, 2025). "Additionally, miR-186-5p is involved in the regulation of cancer cell migration and invasion, and miR-186-5p promotes metastasis by regulating epithelial-to-mesenchymal transition (EMT) markers, such as E-cadherin and vimentin." (PMID 40867269, 2025). "We previously showed that nestin inhibits the binding of vimentin’s tail domain to actin filaments (AFs) by steric hindrance through its large nestin tail domain (NTD), thereby increasing three-dimensional cytoskeleton network mobility, enhancing cell flexibility, and promoting cancer progression." (PMID 39851565, 2025). "On the contrary, MMP9 seemed completely nonspecific and not correlated to an increase in cancer cell aggressiveness, while other genes such as VIM, CDH5, and MCAM showed a trend toward an increased expression in the metastatic counterpart, albeit not statistically significant." (PMID 40332096, 2025). "We have found previously that MErT in cancer involves increased epithelial marker expression (connexin 26/43 and E-cadherin) alongside persistent mesenchymal markers (vimentin and FSP1), revealing that phenotypic switching is not just plastic but often incomplete." (PMID 40940728, 2025). "The injected exp‐CAF2 cells (human vimentin‐positive) were detected in considerable numbers in 30‐day‐old primary tumors, demonstrating that exp‐CAF2 cells present in advanced tumors could continuously produce TGF‐β1 to influence nearby carcinoma cells." (PMID 40644310, 2025). "Furthermore, treatment with iTGFBI or a neutralizing antibody did not affect the expression of vimentin and Src phosphorylation in either the control or Cat D KO cancer cells." (PMID 38297161, 2024). "Interestingly, LRRC15, a protein previously identified in cancer myofibroblasts, was highly expressed in corneal myofibroblasts, both with and without vimentin." (PMID 38994947, 2024).
cancer (continued). "Cancer cells undergoing EMT display both morphological and molecular alterations, which is evidenced by the downregulation of epithelial markers, such as E-cadherin and ZO-1, and upregulation of mesenchymal markers, including N-cadherin, vimentin, fibroblast-specific protein 1, and fibronectin." (PMID 38402159, 2024). "Furthermore, we found increased expression of EMT markers, including N-cadherin (CDH2), vimentin (VIM) and Snail (SNAL1), suggesting that B7-H3 may enhance the EGFR-ERK signaling pathway for cancer cell growth and metastasis." (PMID 38370387, 2024). "REVs were found to enhance the expression of CAFs related proteins like αSMA, CD95, EMT marker vimentin, SLC1A5, and STAT3 phosphorylation as well as FAP expression after 48 hours exposure to REVs and SEVs suggesting that REVs can subvert stromal fibroblasts to adopt a cancer-promoting phenotype." (PMID 39431017, 2024). "Thus, the observed increase in vimentin, along with a normal/high FEV1% value, could be driven by the central role of EMT in the development and progression of carcinomas, as also suggested by data in the literature." (PMID 38276115, 2024). "Several models using diverse cancer types have demonstrated that Withaferin A treatment inhibits experimental epithelial to mesenchymal transition (EMT), and inhibition of this event may be attributed to its impact on vimentin assembly." (PMID 36701406, 2023). "Vimentin is a type III intermediate filament protein expressed in stroma and an important marker of epithelial mesenchymal transition (EMT), an important factor leading to malignant tumor metastasis, and vimentin is an important protein to maintain the cytoskeleton structure." (PMID 37477531, 2023). "Our findings highlighted that PRMT6 overexpression significantly elevated the expression of Vimentin, twist, and N-cadherin, while concurrently downregulating E-cadherin expression in cancer cells expressing STAT3 WT, but not in those expressing STAT3 R729K mutant." (PMID 37813837, 2023). "In this study, we isolated CTCs from prostate (n = 17) and pancreatic (n = 5) cancer patients using a disposable lateral magnetophoretic microseparator, comparing the isolated CTC count, white blood cell (WBC) depletion rate, and CTC purity based on the EpCAM and vimentin antibodies combination." (PMID 37345161, 2023). "To identify whether cancer migration and invasion are involved in EMT, we explore the effect of RAB14 on EMT markers, including epithelial marker (E-cadherin) and mesenchymal marker (vimentin)." (PMID 37558664, 2023). "In another study, withaferin A was found to bind strongly to vimentin and heterogeneous nuclear ribonucleoprotein hnRNP-K, and downregulate the expression of MMPs and VEGF, as well as reduce vimentin, N-cadherin cytoskeleton proteins, and protease u-PA involved in the cancer cell metastasis." (PMID 37259311, 2023). "Histopathological examination and IHC of the biopsy samples were crucial for providing a definitive diagnosis, revealing poorly differentiated, invasive malignant neoplasms that were positive for cytokeratin (AE1/AE3) and negative for vimentin, and therefore consistent with carcinoma." (PMID 38105775, 2023). "Additionally, HBECs treated by highly metastatic cell-derived exosomes and late stage cancer serum-derived exosomes had higher VIM expression compared to HBECs treated by nonmetastatic cell-derived exosomes and healthy serum-derived exosomes, respectively." (PMID 35158999, 2022). "Interestingly, while VIM expression was different in cancer types depending on EMT nature, CDH1 expression did not correlate with the EMT nature of the cancers." (PMID 36120580, 2022). "Hence, no wonder that most studies designated the significance of vimentin as a biomarker in cancers with clinical relevance in several types of cancers and the more in depth information can be found elsewhere." (PMID 35573702, 2022).